FGFR1 (fibroblast growth factor receptor 1)
Diseases named in the same sentence as FGFR1 in open-access papers (continued):
Sharing a sentence is not in itself a finding about the gene and the disease.
cryptorchidism (8 papers, 2017 to 2024). The failure of one or both testes of a male fetus to descend from the abdomen into the scrotum during the late part of pregnancy. "Previous studies on HH in adults reported that patients with FGFR1 mutations had a high incidence of cryptorchidism, small testicular size, long treatment time for spermatogenesis, and low sperm concentration." (PMID 35669683, 2022). "Patients with FGFR1 mutations have a higher prevalence of cryptorchidism and smaller testicular volume." (PMID 33354214, 2020). "The incidence of cryptorchidism in patients with FGFR1, ANOS1, and CHD7 mutations is 50–60%, 38.1–66%, and 50–70%, respectively." (PMID 33354214, 2020). "Patients with FGFR1 mutations have a more severe impairment of the reproductive phenotype, mainly manifested by a high incidence of cryptorchidism and smaller testis volume during spermatogenesis treatment." (PMID 33354214, 2020). "In this study, two patients with FGFR1 gene mutations and cryptorchidism history had a failure of spermatogenesis after two years of treatment." (PMID 33354214, 2020). "In conclusion, gonadal axis defects were more severe in CHH patients with FGFR1 mutations, presenting a higher incidence of cryptorchidism, smaller testicular size, and longer time required for sperm production." (PMID 33354214, 2020). "Patient 5, a 31-year-old male with CHH and associated clinical characteristics of cryptorchidism and micropenis, was found to carry the novel AD p.Pro186Ala in the FGFR1 gene." (PMID 32982993, 2020). "Our study found that the incidence of cryptorchidism in patients with FGFR1 gene mutations was 50%, which is consistent with previous studies." (PMID 33354214, 2020). "Moreover, FGFR1 mutations have been described in cases of idiopathic hypogonadotropic hypogonadism and cryptorchidism." (PMID 29163975, 2017). "It appears likely that, in humans and rodents with cryptorchidism, the impairment in FGFR1 protein secretion in the abnormal mesenchyme contributes to epididymis malformation and the lack of epididymis-testes descent." (PMID 35725394, 2022). "In 2010, we reported that boys with unilateral cryptorchidism showed impaired FGFR1 expression in the undescended testis." (PMID 35725394, 2022). "The previously reported AD p.Arg822Cys also in the FGFR1 gene was found in patient 6, a 20-year-old male with CHH and associated clinical characteristics of cryptorchidism, micropenis and gynaecomastia." (PMID 32982993, 2020). "There were seven cases of cryptorchidism in the FGFR1 group (50.0%): three were unilateral and four were bilateral." (PMID 33354214, 2020). "The incidence of cryptorchidism was up to 67% in patients with KAL1 mutation, while 20% in patients was caused by FGFR1 mutations." (PMID 31929795, 2019). "Causal P and LP variants were identified in 5 out of 13 patients with a history of cryptorchidism (three in FGFR1, one in ARHGAP5, and one in GNRH1), in 2 out of 8 patients with hearing impairment (CHD7 and FGFR1 genes), and in 2 out of 2 patients with renal agenesis (ANOS1 gene)." (PMID 39308770, 2024). "However, in this study, compared with patients with non-FGFR1 mutations, the incidence of cryptorchidism in patients with FGFR1 mutations was not significantly higher, the testicular volume was not small, and the patients with FGFR1 mutations were mainly pure CHH." (PMID 35669683, 2022). "Based on our results, a subtle dysfunction (expression) of FGFR1, SOS1 and RAF1 is possibly involved in the development of unilateral or bilateral cryptorchidism." (PMID 29163975, 2017).
ganglioglioma (8 papers, 2017 to 2026). A well differentiated, slow growing neuroepithelial neoplasm composed of neoplastic, mature ganglion cells and neoplastic glial cells. "While the majority of DNETs and RGNTs harbor FGFR1 mutation or rearrangement, this is only present in a small subset of pathologically-confirmed gangliogliomas." (PMID 29880043, 2018). "The most notable of these are the presence of BRAF-V600E mutations in a subset of ganglioglioma and FGFR1 abnormalities in a portion of DNETs." (PMID 29058119, 2018).
Hypertension (8 papers, 2017 to 2025). The presence of chronic increased pressure in the systemic arterial system. "It was later hypothesized that FGF23 induced the activation of FGFR1, leading to Ace2 reduction, causing hypertension." (PMID 32982979, 2020). "Studies suggest that FGFR1 promotes the fibrotic response of renal tubular epithelial cells in the context of hypertension and elevated angiotensin II, indicating that FGFR1 is a potential target for preserving kidney function and integrity." (PMID 39431155, 2024). "According to the inference, genistein binds to the FGF1 protein in fibroblasts of the skin; the FGF1 protein activates the FGFR1 protein in the muscle cells of the heart; FGFR1 protein activates the UBC protein; the UBC protein activates the CTGF protein, and CTGF affects hypertension." (PMID 31138123, 2019).
hypogonadism (8 papers, 2009 to 2025). A disorder characterized by decreased function of the gonads. "Concerning variant recurrence, the heterozygous mutation in FGFR1 p.R285W (likely pathogenic; CM063987 HGMD), coexisting with another heterozygous variant CHD7 p.N1030H (pathogenic; novel), was recurring in two unrelated patients, both with reversal of hypogonadism." (PMID 34198905, 2021). "In a long-term clinical follow-up, three unrelated subjects with digenic defects (proband 9: CHD7 p.N1030H and FGFR1 p.R285W; proband 10: CHD7 p.N1030H and FGFR1 p.R285W; and proband 25: GNRHR p.R139H, GNRHR p.N10_Q11delinsKK, and CHD7 p.K683_T684insAK) displayed a reversal of hypogonadism." (PMID 34198905, 2021).
hypophosphatemia (8 papers, 2013 to 2025). Lower than normal levels of phosphates in the circulating blood. "This strongly suggests that the expression of the Fgfr1+/N330I variant in bone drives FGF23 excess leading to hypophosphatemia, which in turn leads to systemic undermineralization of bone." (PMID 41473314, 2025). "In humans, osteoglophonic dysplasia caused by activating variants in FGFR1 is often associated with hypophosphatemia due to elevated FGF23 levels." (PMID 35909535, 2022). "However, a human disease called osteoglophonic dysplasia caused by activating mutations in FGFR1 is often associated with hypophosphatemia due to increased FGF23 levels, which also suggests the regulation of FGF23 production by FGFR signaling." (PMID 30972027, 2019). "PMTs are rare FN1-fusion-associated neoplasms of uncertain histogenesis and typically induce osteomalacia and hypophosphatemia due to FGFR1 induced secretion of Fibroblast growth factor 23 (FGF23)." (PMID 39404883, 2025). "We used CRISPR/Cas9 technology to generate a knock-in mouse model expressing the disease-causing FGFR1 variant, p.N330I, chosen because of its frequency and its association with FGF23 excess and hypophosphatemia in patients." (PMID 41473314, 2025). "Here we report that pharmacological activation of FGFR1 with monoclonal anti-FGFR1 antibodies (R1MAb) in adult mice is sufficient to cause an elevation in serum FGF23 and mild hypophosphatemia." (PMID 23451204, 2013). "Together with our results, it is conceivable that genetic activation of FGFR1 in bones leads to elevated FGF23 in OGD, resulting in hypophosphatemia." (PMID 23451204, 2013). "In addition, the conditional deletion of Fgfr1 in osteocytes partially restored the FGF23 overproduction and rescued the hypophosphatemia and mineralization defect in Hyp mice." (PMID 30972027, 2019). "Moreover, pharmacological activation of FGFR1 by monoclonal antibodies in adult mice led to increased serum FGF23 levels and mild hypophosphatemia, and the same monoclonal antibody in cultured rat calvarial osteoblasts induced Fgf23 mRNA expression and protein secretion into the culture medium." (PMID 41473314, 2025). "In a subsequent study, however, FGF23 did not reduce serum phosphorus levels in double Fgfr3/Fgfr4 KO mice, suggesting that FGFR3 and FGFR4 play redundant roles in phosphate regulation, and perhaps that FGFR1 activation is not sufficient for FGF23 to induce hypophosphatemia." (PMID 23451204, 2013). "Our results demonstrate that activation of FGFR1, but not other FGFRs, is sufficient to induce FGF23 expression and the resulting hypophosphatemia in adult mice." (PMID 23451204, 2013). "Intriguingly, pharmacological activation of FGFR1 by R1MAb1 injection did not result in an apparent defect in bone mineral density in db/db mice despite the ability of R1MAb1 to induce FGF23 production and hypophosphatemia." (PMID 23451204, 2013).
medulloblastoma (8 papers, 2015 to 2025). A malignant, invasive embryonal neoplasm arising from the cerebellum. "On the contrary, preclinical study in medulloblastoma showed antagonistic role between FGFR1 and GLI1 expression, suggesting tissue-specific role of these pathways." (PMID 34722544, 2021). "Fibroblast growth factor receptor (FGFR) signaling is known to drive SHH medulloblastomas and is critical in regulating medulloblastoma invasion, and FGFR1 has been demonstrated to mediate inhibition of SHH medulloblastoma growth." (PMID 32508873, 2020). "Therefore, we started to screen the expression of VEGFR1-3, PDGFRα/β, MET, FGFR1-2 and ErbB1-4 on the cell surface of 5 medulloblastoma cell lines." (PMID 26496080, 2015). "Additionally, these modules were interconnected via several hub genes, namely, FGFR1, BMP4, PAX6, PAX3, SOX9, and GLI2, all of which have been related to medulloblastomas in previous studies." (PMID 32508873, 2020). "As a comparison, we assessed two medulloblastoma cases (NMB361 and NMB795), which showed nuclear staining for SMARCB1 and were negative for both PDGFRα and FGFR1." (PMID 27783942, 2016).
neuroepithelial tumors (8 papers, 2017 to 2025). "Recent molecular genetic studies have revealed various mutations in the mitogen-activated protein kinase (MAPK) pathway, including BRAF and FGFR1, in low-grade neuroepithelial tumors; however, associations between genotypes and pathological findings remain unclear." (PMID 39081340, 2024). "In our study, pathogenic variants in FGFR1 and PIK3R1 were identified in two patients with neuroepithelial tumors, with VAFs ranging from 24–36%." (PMID 39859528, 2025). "Our study sought to refine classification of low-grade neuroepithelial tumors (LGNET) harboring FGFR1 alterations by investigating if the specific type of FGFR1 alteration, accompanying genetic alterations, tumor location, and epigenetic signature can help to more accurately stratify these tumors." (PMID 32859279, 2020). "These include FGFR1 tyrosine kinase domain duplication in low grade glioma, FGFR1-TACC1 fusions in extraventricular neurocytoma (EVN), and FGFR2-CTNNA3 fusions in polymorphous low grade neuroepithelial tumor of the young (PLNTY)." (PMID 32085805, 2020).
oligodendroglioma (8 papers, 2017 to 2025). A well-differentiated (WHO grade II), diffusely infiltrating neuroglial tumor, typically located in the cerebral hemispheres. "The FGFR1 mutant case was a 34-year-old male with diagnosis of oligodendroglioma grade II." (PMID 35018490, 2022). "However, in IDH1 wild-type cases, pediatric oligodendrogliomas most frequently harbor alterations in FGFR1 including TKD-duplications or SNVs or BRAF p.V600E." (PMID 32164789, 2020). "Other interesting alterations involving FGFR1 detected in this series of tumors were two FGFR1::TACC1 fusions found in one anaplastic PA (P4551_218T) and one oligodendroglioma (P7708_105T)." (PMID 37221626, 2023).
pulmonary fibrosis (8 papers, 2014 to 2024). Chronic progressive interstitial lung disorder characterized by the replacement of the lung tissue by connective tissue, leading to progressive dyspnea, respiratory failure, or right heart failure. "Research on fibrotic diseases has described significant FGFR1 expression in idiopathic pulmonary fibrosis (IPF) patients, which is associated with fibroblast migration and increased MAPK-signaling, contributing to the pathogenesis of IPF." (PMID 38137441, 2023). "Other important mediators associated with lung fibrosis are legumain, osteopontin, IL-4, IL-6, IL-13, IL-17, TNF-α, Gal-1, Gal-3, PDGF, and FGFR-1." (PMID 38540252, 2024). "As FGFR1 has been proven to be essential for tissue regeneration and pulmonary fibrosis, we first detected FGFR1 expression in human keloid tissues." (PMID 38137441, 2023). "Studies have shown that fibroblast growth factor receptor-1 (FGFR1) was enhanced in pathological fibrous proliferation diseases, such as cirrhosis and idiopathic pulmonary fibrosis (IPF), suggesting the FGFR1 pathway has potential for keloid treatment." (PMID 38137441, 2023). "Despite different viewpoints, the FGFR1‐mediated signal was closely related to pulmonary fibrosis." (PMID 33135394, 2020). "The pathogenesis of pulmonary fibrosis involves various mediators such as TGF-β, legumain, osteopontin, IL-4, IL-6, IL-13, IL-17, TNF-α, Gal-1, Gal-3, PDGF, and FGFR-1." (PMID 38540252, 2024). "Combined with the up‐regulation of miR‐503 in a mouse model of silica‐induced pulmonary fibrosis, we revealed that miR‐503 mitigated the TGF‐β1‐induced effects in fibroblasts by regulating VEGFA and FGFR1 and then affecting the MAPK/ERK signalling pathway." (PMID 33135394, 2020). "Mechanistically, miR‐503 co‐targeted VEGFA and FGFR1, and then blocked the MAPK/ERK pathway, thus alleviating silica‐induced pulmonary fibrosis." (PMID 33135394, 2020). "A multi-kinase inhibitor (nintedanib), which suppresses FGFR1–3, was also recently FDA-approved for idiopathic pulmonary fibrosis." (PMID 26224133, 2015). "Earlier kinase activity assays showed that YTH‐60 has the best inhibitory effect on FGFR1, thus we choose FGFR1 as the target of drug action and used the clinical drug Nintedanib as a positive control and evaluated the effects of YTH‐60 against pulmonary fibrosis in in vivo studies." (PMID 34121240, 2021). "Therefore, we reasoned that miR‐503 negatively regulated the TGF‐β1‐induced effects in fibroblast by co‐targeting VEGFA and FGFR1 to affect the MAPK/ERK pathway, thus alleviating silica‐induced pulmonary fibrosis." (PMID 33135394, 2020). "However, it is not clear whether miR‐503 plays a regulatory role by jointly targeting VEGFA and FGFR1 in silica‐induced pulmonary fibrosis and whether there is a synergistic effect between VEGFA and FGFR1." (PMID 33135394, 2020).
acute lymphoblastic leukemia (7 papers, 2012 to 2025). Leukemia with an acute onset, characterized by the presence of lymphoblasts in the bone marrow and the peripheral blood. "The ZMYM2-FGFR1 fusion protein contains the zinc finger domain of ZMYM2, mediating the constitutive activation of FGFR1 and causing sustained activation of the Notch pathway, which is closely related to the development of T-cell acute lymphoblastic leukemia (T-ALL)." (PMID 39590377, 2024). "When miR-146b-5p expression levels were analyzed in the GSE79547 human B-cell precursor acute lymphoblastic leukemia data set, there was a significant inverse correlation between miR-146b-5p expression and FGFR1 expression." (PMID 34906138, 2021). "Despite the emergence of drug resistance, precision treatment with a combined synergistic effect of mTOR and fibroblast growth factor receptor 1 (FGFR1) inhibitors is promising for T-cell acute lymphoblastic leukemia (T-ALL)." (PMID 39484162, 2024). "By frequency, pediatric soft tissue sarcoma had the highest percentage of FGFR1-4 gene alterations, followed by atypical teratoid-rhabdoid tumors (ATRT), pediatric T-cell acute lymphoblastic leukemia (T-ALL), and B-cell lymphoblastic ALL (B-ALL)." (PMID 40510032, 2025).
cleft lip (7 papers, 2009 to 2024). Congenital defect in the upper lip where the maxillary prominence fails to merge with the merged medial nasal prominences. "Some specificities were observed such as one patient presenting with a history of cleft palate, cleft lip and a normal sense of smell, suggesting a mutation of fibroblast growth factor receptor 1 (FGFR1) or a mutation in FGF8." (PMID 31448010, 2019). "Two novel heterozygous missense mutations in FGFR1, (NM_001174066): c.776G>A (p.G259E) and (NM_001174066): c.358C>T (p.R120C), were identified in a 23-year-old KS male with cleft lip and an 18-year-old KS patient with cleft lip and palate, dental agenesis, and high arched palate, respectively." (PMID 26199944, 2015). "In the group with a nonreproductive phenotype, variants in the FGFR1 gene were found in one patient with cleft lip and palate, which was consistent with the report of a previous study." (PMID 35090434, 2022). "Nevertheless, CL/P and CP can segregate in the same family, with etiologic mutations in genes such as FGFR1, IRF6, MSX1 and P63, and epidemiologic data suggest that cleft lip only may have unique etiologic features." (PMID 31652620, 2019). "One of the KS patients also carried the PROKR2 (p.Y113H) mutation, which has similar clinical manifestations to the patients in this study; the other KS patient who carried both FGFR1 (p.Gly348Glu) and RUVBL2 (p.Arg71Trp) only showed non-reproductive symptoms associated with cleft lip and palate." (PMID 38628584, 2024).
diffuse midline glioma (7 papers, 2017 to 2024). A diffuse glioma that arises from the midline structures of the central nervous system. "Patient 17 and 18 with radiologically recurrent H3K27-altered diffuse midline glioma and FGFR1 mutations were treated with the FGFR1/2/3 inhibitor pemigatinib." (PMID 35864412, 2022). "This FGFR1 mutation has previously been reported in diffuse midline gliomas." (PMID 35864412, 2022). "Nonetheless, actionable key driver mutations are rare in primary brain cancers and frequently analyses yield variants with unclear oncogenic driver potential as illustrated by the example of the two young patients with recurrent H3 K27-altered diffuse midline glioma and FGFR1 mutations." (PMID 35864412, 2022). "Accounting for all these differences, they propose the new category of diffuse midline glioma, H3K27 and BRAF/FGFR1 co-altered." (PMID 39126064, 2024).
invasive breast carcinoma (7 papers, 2012 to 2023). A carcinoma that infiltrates the breast parenchyma. "FGFR1 amplification is more commonly seen in invasive breast carcinoma tissue than in the ductal carcinoma in situ (DCIS)." (PMID 30713601, 2019). "FGFR1 copy number variation was assessed in 281 of the 283 invasive breast cancers by FISH (all the tissue microarray cores has been lost in two cases)." (PMID 29228597, 2017).
low grade glioma (7 papers, 2018 to 2025). A grade I or grade II glioma arising from the central nervous system. "Additional FGFR1 missense mutations in cis have been reported in low-grade gliomas (LGGs) developed by ECCL individuals classified as midline pilocytic astrocytomas, providing additional evidence for a driver role of multiple FGFR1 mutations in LGGs/LGGNTs." (PMID 41174249, 2025). "The current study examined 50 out of 67 pediatric patients with low-grade gliomas (LGGs) who had genomic testing between 2011 and 2022 at our institution to determine whether a correlation exists between FGFR1 mutations and spontaneous ICH." (PMID 38903142, 2024). "Alterations in cell growth pathways are seen in some pHGGs, including BRAF and FGFR1 mutations and gene fusions among the TRK family (NTRK1/2/3); however, BRAF/FGFR1 perturbations are far more prominent in pediatric low-grade gliomas (pLGGs)." (PMID 30340362, 2018).